ANKRD7 (ankyrin repeat domain 7)
Synonyms: TSA806
Tractability: No criterion of Open Targets' tractability assessment is met for any kind of drug.
Gene: Protein-coding gene on chromosome 7 (118,214,669 to 118,496,171, forward strand). Ensembl gene ENSG00000106013.
Subcellular location (Human Protein Atlas): Nucleoplasm
Gene Ontology:
Cellular component: nucleoplasm
Genetic constraint (gnomAD): Loss-of-function variants: 19 observed, 22.87 expected, observed/expected ratio (o/e) 0.83, 90% interval 0.58 to 1.22. The upper end of that interval is the gene's LOEUF score, 1.22, which puts it in group 5 of 6, group 1 being the genes least tolerant of losing a copy. Missense variants: 207 observed, 239.14 expected, observed/expected ratio (o/e) 0.87, 90% interval 0.77 to 0.97. Synonymous variants: 73 observed, 84.88 expected, observed/expected ratio (o/e) 0.86, 90% interval 0.71 to 1.04.
Homologues: Orthologues: chimpanzee ANKRD7 (100% identical), macaque ANKRD7 (86% identical). Paralogues in human: MTPN (17% identical).
Diseases named in the same sentence as ANKRD7 in open-access papers:
ANKRD7 is named in the same sentence as 3 diseases in open-access papers, as found by Europe PMC text mining. Sharing a sentence is not in itself a finding about the gene and the disease. The quoted sentences say what the papers report.
oligospermia (1 paper, 2017). Decreased number of spermatozoa in the semen. "Three down-regulated genes (PLCZ1, TSSK2 and ANKRD7) were common between MArrest, oligospermia and the Dazap1 mouse mutant." (PMID 29150651, 2017).
ANKRD7 also shares sentences with these, for which no sentence is quoted: Allergy (1 paper); Ovarian cyst (1).